TULP3 (TUB like protein 3)
Description:
Protein-protein adapter that drives transport of G protein-coupled receptors into primary cilia by mediating association between the intraflagellar transport complex A (IFT-A) and G protein-coupled receptors FFAR4, GPR45 and GPR161. Acts as a negative regulator of the Shh signaling by promoting trafficking of GPR161 to cilia. During adipogenesis, regulates ciliary trafficking of FFAR4 in preadipocytes. Promotes transport of GPR45 into primary cilia of neurons in paraventricular nucleus (PVN) of the hypothalamus (By similarity). Binds to phosphorylated inositide (phosphoinositide) lipids; both IFT-A- and phosphoinositide-binding properties are required to regulate ciliary G protein-coupled receptor trafficking. Besides its role in cilium localization, acts as a regulator of AMP-activated protein kinase (AMPK) activity in response to calorie restriction: binds lithocholic acid, a metabolite generated in response to calorie restriction, promoting TULP3 ability to activate SIRT1, which then deacetylates the ATP6V1E1 subunit of the V-ATPase complex, leading to (1) V-ATPase complex inhibition on lysosomes and (2) AMPK activation via the AXIN1-STK11/LKB1 axis (By similarity).
Synonyms: TUBL3; HRCDF
Tractability: Antibody: its Gene Ontology location is reachable by antibodies, with high confidence; UniProt places it where antibodies can reach, with medium confidence; the Human Protein Atlas places it where antibodies can reach. PROTAC: ubiquitination databases record sites on it; its protein half-life has been measured.
Gene: Protein-coding gene on chromosome 12 (2,877,223 to 2,941,138, forward strand). Ensembl gene ENSG00000078246.
Subcellular location: Cell projection, cilium; Cell membrane; Nucleus; Cytoplasm; Secreted
Subcellular location (Human Protein Atlas): Nucleoplasm; Primary cilium; Basal body; Mitotic spindle; Nucleoli; Plasma membrane; Primary cilium transition zone
Pathways (Reactome):
Signal Transduction: Hedgehog 'off' state
Gene Ontology:
Molecular function: enzyme binding; G protein-coupled receptor binding; intraciliary transport particle A binding; phosphatidylinositol binding; protein binding; protein-containing complex binding; protein-macromolecule adaptor activity; lithocholic acid binding; phosphatidylinositol-4,5-bisphosphate binding
Biological process: intraciliary anterograde transport; negative regulation of smoothened signaling pathway; protein localization to cilium; protein localization to non-motile cilium; regulation of G protein-coupled receptor signaling pathway; cellular response to glucose starvation; G protein-coupled receptor signaling pathway; negative regulation of TORC1 signaling; regulation of DNA-templated transcription
Cellular component: 9+0 non-motile cilium; ciliary base; ciliary transition zone; cilium; nucleolus; nucleoplasm; nucleus; plasma membrane; axoneme; cytoplasm; extracellular region
Genetic constraint (gnomAD): Loss-of-function variants: 33 observed, 41.67 expected, observed/expected ratio (o/e) 0.79, 90% interval 0.6 to 1.06. The upper end of that interval is the gene's LOEUF score, 1.06, which puts it in group 4 of 6, group 1 being the genes least tolerant of losing a copy. Missense variants: 516 observed, 551.5 expected, observed/expected ratio (o/e) 0.94, 90% interval 0.87 to 1.01. Synonymous variants: 175 observed, 193.35 expected, observed/expected ratio (o/e) 0.91, 90% interval 0.8 to 1.03.
Gene-disease validity (ClinGen):
ClinGen rates the evidence that TULP3 causes each of these diseases.
ciliopathy (autosomal recessive): Strong. A genetic disorder of the cellular cilia or the cilia anchoring structures, the basal bodies, or of ciliary function.
Homologues: Orthologues: chimpanzee TULP3 (99% identical), macaque TULP3 (89% identical), pig TULP3 (74% identical), rabbit TULP3 (73% identical), rat Tulp3 (73% identical), guinea pig TULP3 (72% identical), mouse Tulp3 (72% identical), zebrafish tulp3 (60% identical), dog TULP3 (55% identical), Drosophila melanogaster ktub (42% identical). Paralogues in human: TUB (55% identical), TULP1 (45% identical), TULP2 (38% identical), TULP4 (24% identical), WDR35 (14% identical).